ERBB2 (erb-b2 receptor tyrosine kinase 2)
Diseases named in the same sentence as ERBB2 in open-access papers (continued):
Sharing a sentence is not in itself a finding about the gene and the disease.
triple-negative breast carcinoma (continued). "Higher risks of triple-negative breast cancer and ERBB2 enriched–like tumors among former OC users (for >5 years) and those who ceased use within the last 10 years and significant heterogeneity by disease subtype (P = .02) are in line with our findings in women with healthy weight." (PMID 40622713, 2025). "Among ERBB2 positive disease, Black patients had a lower percentage of very sensitive disease (32% vs 37%-40%; P < .001) and among triple-negative breast cancer, more refractory disease was seen among Black patients compared with other races and ethnicities (38% vs 30%-35%; P < .001)." (PMID 37991763, 2023). "It is very heterogeneous, and, based on hormone receptor (ER and PR) and HER2 (ERBB2) status, can be clinically divided into luminal ER-positive and PR-positive, and further subdivided into luminal A and B, HER2-positive and triple negative breast cancer (TNBC)." (PMID 36765522, 2023). "Interestingly, higher levels of MERIT40 were observed in triple-negative breast cancers (ER/PR− ERBB2−) as compared to luminal tumors (ER/PR+ ERBB2−)." (PMID 37248434, 2023). "Despite ERBB3/HER3 and its partner ERBB2/HER2 showing low expression levels in basal-like/triple-negative breast cancers, stratification of basal-like patients according to ERBB3 mRNA expression levels highlighted a correlation between higher ERBB3 levels and shorter relapse-free patients’ survival." (PMID 35406375, 2022). "A rearrangement between MAGI3 and AKT3 genes caused by chromosome 1 inversion, has been identified in triple-negative breast cancer (lacking estrogen and progesterone receptors and ERBB2 expression)." (PMID 34503076, 2021). "Furthermore, a clinical investigation of HER2+ breast tissues revealed a strong protein interaction between CHRNA9 and ERBB2 compared to that in triple-negative breast cancer (TNBC) breast tissues." (PMID 31311925, 2019). "Such higher activity correlated with increased acetylation of histones and alfa-tubulin as a consequence of HDAC inhibitor-mediated epigenetic modulation that also induced increased expression of ErbB2 and estrogen receptor in triple negative breast cancer cells." (PMID 32039017, 2019). "Interestingly, ST8176AA1 also induced ErbB2 and ERα expression in triple negative breast cancer cells thus possibly making this orphan tumor, sensitive to standard treatments." (PMID 32039017, 2019). "This contrasts with the observations that triple-negative breast cancers (that lack ErbB2) may show a good response to Hsp90 inhibitors." (PMID 30138434, 2018). "BCa is often classified clinically into four subtypes based on expression of ER, progesterone receptor (PR), and human epidermal growth factor receptor 2 (HER2, also known as ERBB2): ER+/PR+/HER2−, ER+/PR+/HER2+, ER−/PR−/HER2+, and ER−/PR−/HER2− (also known as triple negative breast cancer, TNBC)." (PMID 28134791, 2017). "Therefore, although this study was conducted on triple negative breast cancer, we were able to detect RNA expression of ERBB2 and ESR1, and found a complex expression pattern among HER family members and the ESR1 gene in TNBC." (PMID 26907936, 2016). "ST8176AA1 could be an alternative or a companion drug to T-DM1 for the treatment of ErbB2+ tumors and a unique therapeutic opportunity for triple negative breast cancer that might be inhibited by ST8176AA1 and also be made sensitive to tamoxifen standard therapies." (PMID 32039017, 2019). "Moreover, patients with ER, progesterone receptor (PR) and human epidermal growth factor receptor 2 (also known as ErbB-2) triple-negative breast cancer, which is aggressive with high recurrence, metastatic and mortality rates, do not respond to hormonal therapies and have limited treatment options." (PMID 26053034, 2015). "ERBB2 status has only recently been included in major registries (eg, since 2010 in SEER), complicating the accurate identification of triple-negative breast cancer cases in earlier datasets." (PMID 40373794, 2025).
triple-negative breast carcinoma (continued). "In triple-negative breast cancer, high expression of XPO1 accelerates proliferation by exporting oncogene mRNAs such as MYC and ERBB2, inhibits mitochondrial release of Cyt c, and weakens apoptotic sensitivity." (PMID 40860340, 2025). "Triple-negative breast cancer (TNBC), a subtype that lacks the expression of the oestrogen receptor, progesterone receptor and amplification of the ERBB2/HER2 gene, is a particularly aggressive form that presents a unique clinical challenge." (PMID 39271910, 2024). "Specifically, the HER2E subtypes are similar to HER2+/HER2E tumors but lack the amplification/ overexpression of the HER2 amplicon (ERBB2 and GRB7); on the other hand, the basal-like subtypes are similar to triple-negative breast cancers." (PMID 35806079, 2022). "Triple negative breast cancers (TNBC) are a group of heterogeneous cancers characterized by their lack of estrogen receptor (ER), progesterone receptor (PR), and ErbB2/HER2/Neu." (PMID 32349331, 2020). "To assess the ability of new compounds to modulate EGFR expression and phosphorylation, we used the triple-negative breast cancer cell line MDA-MB-468, in which the receptor protein is overexpressed compared with the low expression of its counterpart ErbB2." (PMID 31374910, 2019). "In particular, triple negative breast cancer (TNBC) comprise a heterogeneous group of basal-like tumors lacking estrogen receptor (ERα), progesterone receptor (PR) and HER2 (ErbB2)." (PMID 30046386, 2018). "Triple negative breast cancer (TNBC) is one subtype that lacks the expression of steroid hormone receptors and HER2/ERBB2 gene amplification or protein overexpression." (PMID 30583472, 2018). "Triple negative breast cancers (TNBCs) are known to express low PGR, ESR1, and ERBB2, and high KRT5, KRT14, and KRT17." (PMID 30335837, 2018). "Triple-negative breast cancers (TNBC) lack estrogen receptor (ER), progesterone receptor (PR), and human epidermal growth factor receptor 2 (ErbB2, Her2), and represent 16% of cases." (PMID 26629823, 2015). "The absence of estrogen and progesterone receptors and the lack of ERBB2/HER2 gene amplification or overexpression characterize triple-negative breast cancer (TNBC)." (PMID 39910592, 2025). "Clinically, breast tumors are categorized based on the expression of estrogen receptor (ER), progesterone receptor (PR), and human epidermal growth factor receptor 2 (HER2/ERBB2) into three main subtypes: ER-positive, HER2-positive, and triple-negative breast cancer (TNBC)." (PMID 41155194, 2025). "Additionally, triple-negative breast cancer (TNBC) is a subtype that lacks expression of ER, PR, and the receptor tyrosine-protein kinase erbB-2 (ERBB2/Her2)." (PMID 39456237, 2024). "The triple negative breast cancer (TNBC) is characterized by a lack of estrogen or progesterone receptor expression as well as of human epidermal growth factor receptor 2 (ERBB2/HER2)." (PMID 38896334, 2024). "The treatment of triple-negative breast cancer (TNBC) is particularly challenging, due to its negligible expression of targetable receptors like estrogen receptor (ER), progesterone receptor (PR), and human epidermal growth factor receptor 2 (HER2/Neu/ErbB2)." (PMID 39057951, 2024). "A study explored the viability of a gene therapy approach to treat the highly malignant triple-negative breast cancer (TNBC), which lacks the expression of ErbB2/HER2, estrogen, and progesterone receptors, by targeting the Ca2+/CaM-dependent kinase eEF-2K, which was highly expressed in these tumors." (PMID 38136610, 2023). "The molecular portrait of BCs is based on the expression of hormone receptors (ER and PR, HER2 (or ErbB-2), or none: basal-like or triple-negative breast cancers (TNBCs))." (PMID 37511924, 2023). "Triple-negative breast cancer (TNBC) comprises a range of BCs with different characteristics that lack an estrogen receptor, a progesterone receptor, and the human epidermal growth factor receptor 2 (ERBB2; formerly known as HER2)." (PMID 38069380, 2023).
triple-negative breast carcinoma (continued). "Triple-negative breast cancer is aggressive in both women and dogs and is characterized by the absence of positivity to hormone receptors (estrogen and progesterone) and human epidermal growth factor receptor-2 (ERBB2/HER2)." (PMID 37483298, 2023). "Triple-negative breast cancer (TNBC) is defined as a tumor that lacks the estrogen and progesterone receptor expression and shows a lack of or decreased expression of erb-b2 receptor tyrosine kinase 2 (ERBB2, also known as HER2)." (PMID 36555509, 2022). "However, there is another group of triple-negative breast cancer (TNBC) patients that lack the expression of ER, PR (PRGR; Progesterone receptor), and HER-2 (ERBB2; Receptor tyrosine-protein kinase erbB-2) receptors." (PMID 33498667, 2021). "Triple-negative breast cancer (TNBC) is a pathological term used to identify invasive breast cancers that lack expression of estrogen and progesterone receptors and do not have pathologic overexpression of the HER2 receptor or harbor ERBB2 gene amplification." (PMID 34888495, 2021). "Triple negative breast cancer (TNBC) poses a serious clinical challenge as it is an aggressive form of the disease that lacks estrogen receptor, progesterone receptor, and ERBB2 (formerly HER2) gene amplification, which limits the treatment options." (PMID 34649623, 2021). "Besides MCF-7 cells, the effect of equol was also measured in ErbB2 positive cells (MDA-MB-453) and triple-negative breast cancer (TNBC) cell lines (ER-, PR-, ErbB2-), which are MDA-MB-468, MDA-MB-231, and HS578t." (PMID 33669783, 2021). "A notable example is triple-negative breast cancer (negative for ERBB2 (Her2/neu), estrogen receptor, and progesterone receptor protein expression), which is typically an aggressive tumor that does not respond to targeted chemotherapy agents." (PMID 34768683, 2021). "Triple-negative breast cancer (TNBC) encompasses a subgroup of tumors defined by absence of estrogen and progesterone receptor expression and lack of amplification of the human epidermal receptor growth factor 2/erythroblastic oncogene B (HER2/ERBB2) gene." (PMID 32719340, 2020). "That was the case for BRCA1, ERBB2 and ERBB3 loci that were found to be deregulated in triple-negative breast cancers or von Hippel-Lindau (VHL) tumour suppressor gene and PRCC that was linked to clear cell renal cell carcinoma and papillary renal cell carcinoma respectively." (PMID 31105870, 2019). "Triple negative breast cancer (TNBC) comprises a heterogeneous group of tumors defined as a basal-like subtype lacking estrogen receptor alpha (ESR1), progesterone receptor (PGR), and human epidermal growth factor receptor 2 (ERBB2)." (PMID 30123188, 2018). "Triple negative breast cancers (TNBCs) are defined by a lack of estrogen receptor expression and progesterone receptor expression, as well as an absence of human epidermal growth factor receptor 2 (ERBB2/HER2) amplification." (PMID 25361177, 2014). "Regarding to the biological markers, which can predict disease prognosis and treatment outcomes, the genotypes were similarly distributed irrespective of the status of ER, PR, erbB2 and Ki67, neither do the receptor status or triple-negative breast cancer." (PMID 21457555, 2011). "Although defined by the absence of estrogen receptor, progesterone receptor, and ERBB2 expression, genomic analyses have revealed intrinsic triple-negative breast cancer subtypes, including basal-like (BL1 and BL2), mesenchymal, luminal androgen receptor, and immunomodulatory subtypes." (PMID 40373794, 2025). "However, our unpublished data indicated that triple-negative breast cancer cells that express NRG do not express ErbB3 or ErbB2." (PMID 36511917, 2023).
triple-negative breast carcinoma (continued). "Despite ERBB3 expression in basal-like/triple-negative breast cancer appearing to be low, our study suggests that the NRG1β/ERBB3/ERBB2 axis in basal-like/triple-negative breast cancer patients may support tumor cell dissemination by promoting anchorage-independent cell growth." (PMID 35406375, 2022). "In vitro analyses unveiled that the activation of the NRG1/ERBB3/ERBB2 axis robustly induces anchorage-independent growth of basal-like/triple-negative breast cancer cellular models, without significant effects on cell proliferation, differentiation, and migration in adhesion." (PMID 35406375, 2022). "In this study, expression of ERBB2 led to autophagy promotion and resistance to cell death in triple-negative breast cancer cells (lack of ERBB2, estrogen (ER) and progesterone (PR)), supporting that in established cancer cells, the level of autophagy correlates with treatment resistance of cancer." (PMID 33801244, 2021). "MDA-MB-231 cells are used extensively as a model for triple-negative breast cancer, based on the lack of expression of cell surface receptors, estrogen receptor (ER), progesterone receptor (PR) and the growth factor receptor, human epidermal growth factor receptor-2 (HER2/ERBB2)." (PMID 34238275, 2021). "However, treatment of triple-negative breast cancers (TNBC) that do not express high levels of HER2/ERBB2, ER, or progesterone receptor (PR) remains a major therapeutic challenge." (PMID 31448050, 2019). "Interestingly, the C19MChigh group harbored significantly downregulated expression of PGR, ESR1 and ERBB2 mRNAs compared to C19MClow group, the candidate “negative markers” of triple negative breast cancers." (PMID 30335837, 2018). "In addition, ERBB2 was overexpressed with or without CTMP overexpression in MB-231 cells (a triple negative breast cancer cell line)." (PMID 27447863, 2017). "Furthermore, expression of a potential negative regulator of E2F6 microRNA-185 (miR-185) is downregulated in triple-negative breast cancer (i.e. negative for estrogen ER, progesterone PgR, and human epidermal growth factor receptor HER2/ERBB2) and associated with poor prognosis." (PMID 31768102, 2019). "Triple-negative breast cancer (TNBC) is characterized by the absence of estrogen receptor (ER), progesterone receptor (PR), and human epidermal growth factor receptor 2 (ErbB2) expression." (PMID 41345520, 2025). "In contrast, triple-negative breast cancer (TNBC) presents a distinct profile, characterized by the absence of estrogen receptor, progesterone receptor, and ErbB2 expression." (PMID 39908697, 2025). "Triple-negative breast cancer (TNBC) is characterized by the lack of ESR (estrogen receptor) and PGR (progesterone receptor) expression and the absence of ERBB2/HER2 (erb-b2 receptor tyrosine kinase 2) overexpression or gene amplification." (PMID 40097917, 2025). "Triple-negative breast cancer (TNBC) is negative for the three current treatment-predictive markers (estrogen receptor, ER, progesterone receptor, PR, and ERBB2/HER2 gene amplification) and constitutes ~10–20% of patients with primary disease." (PMID 40155623, 2025). "Triple-negative breast cancer (TNBC) is defined by the absence of the estrogen receptor (ERα), progesterone receptor (PR), and the human epidermal growth factor receptor-2 (ERBB2/HER2) in tumor cells." (PMID 39171293, 2024). "CpG island promoter methylation is more common in young women with high-grade pathology and triple-negative breast cancer (negative estrogen receptor, negative progesterone receptor, negative ERBB2 [Her2/Neu])." (PMID 37108398, 2023). "The definition of triple-negative breast cancer (TNBC) is the lack of expression of estrogen receptors (ERs) as well as progesterone receptors (PRs) and Erb-B2 receptor tyrosine kinase 2 (HER2) gene amplification." (PMID 37621828, 2023).
triple-negative breast carcinoma (continued). "Triple-negative breast cancer (TNBC) is defined by a lack of expression of the estrogen receptor (ER) and progesterone receptor (PR) and lack of overexpression of the human epidermal growth factor receptor 2 (HER2, ERBB2)." (PMID 35734391, 2022). "Triple-negative breast cancer (TNBC) is characterized by the lack of detectible expression of estrogen receptor (ER), progesterone receptor (PR), and human epidermal growth factor receptor 2 (HER2/Neu/ErbB2)." (PMID 30587795, 2018). "Triple-negative breast cancer (TNBC) is defined by the lack of expression of both estrogen and progesterone receptors and the absence of ERBB2 (HER2) over-expression." (PMID 30294328, 2018). "Triple-negative breast cancer (TNBC), which does not express estrogen receptor, progesterone receptor, and HER2 (ERBB2, Erb-B2 receptor), represents an imperative therapeutic need due to its highly invasive nature and relatively poor response to existing treatments." (PMID 39041239, 2024). "The definition of triple-negative breast cancer (TNBC) is the lack of expression of estrogen receptors (ERs) as well as progesterone receptors (PRs) and Erb-B2 receptor tyrosine kinase 2 gene amplification (HER2)." (PMID 37621828, 2023). "On the other hand, long-term prognosis and therapeutic options are much poorer in triple-negative breast cancers (TNBC), which by definition do not express ERα and progesterone receptor (PR), and do not overexpress the receptor tyrosine-protein kinase erbB-2 (HER2)." (PMID 36902090, 2023). "Triple-negative breast cancer (TNBC) is clinically defined by the absence of estrogen and progesterone receptors and the lack of membrane overexpression or gene amplification of receptor tyrosine kinase ErbB-2/HER2." (PMID 35534460, 2022). "Triple-negative breast cancer (TNBC) is clinically defined by the absence of estrogen and progesterone receptors and lack of overexpression at the plasma membrane (PM) of ErbB-2/HER2 (MErbB-2), a member of the ErbB family of tyrosine kinase receptors, or of ERBB2 gene amplification." (PMID 35534460, 2022). "Triple-negative breast cancer (TNBC), accounting for about 15–20% of total, is a subtype characterized by lack of estrogen receptor (ER) and progesterone receptor (PR) expression and lack of ERBB2 (also known as HER2) amplification." (PMID 33791304, 2021). "Triple-negative breast cancer (TNBC) is characterized by a lack of expression of estrogen receptor (ER), progesterone receptor (PR) and ErbB-2/human epidermal growth factor receptor 2 (HER2)." (PMID 25104095, 2014). "Patients with triple-negative breast cancer (TNBC), clinically defined by their minimal expression or absence of estrogen receptor, progesterone receptor, and receptor tyrosine-protein kinase erbB-2 (HER2), have poor prognosis due to the lack of effective molecular targeting therapies." (PMID 37966117, 2023).